IDUA (alpha-L-iduronidase)
Diseases named in the same sentence as IDUA in open-access papers (continued):
Sharing a sentence is not in itself a finding about the gene and the disease.
osteoporosis (2 papers, 2019 to 2023). A condition of reduced bone mass, with decreased cortical thickness and a decrease in the number and size of the trabeculae of cancellous bone (but normal chemical composition), resulting in increased fracture incidence. "Osteoporosis (OP) is a common polygenic disorder in the aging population, and several single nucleotide polymorphisms (SNPs) in the alpha-L-iduronidase (IDUA) gene and patched homolog 1 (PTCH1) gene regulate bone metabolism and affect bone mass." (PMID 31275456, 2019). "Multiple proteins that showed strong evidence to be associated with osteoporosis-related traits were supported by previous studies, such as RSPO3, IDUA, SMOC2." (PMID 37448626, 2023).
ovarian carcinoma (2 papers, 2020 to 2023). A malignant neoplasm originating from the surface ovarian epithelium. "In addition, they analyzed the expression of IDUA in ovarian cancer cells." (PMID 37601653, 2023). "We further analyzed the differential expression of B3GAT3, COL5A1, FAM162A, IDUA, and PPP2R1A in ovarian cancer SKOV-3 and A2780 cells and HOSEpiC human ovarian epithelial cells." (PMID 33281878, 2020). "The RT-qPCR results showed that compared with human ovarian epithelial cells, the expression of B3GAT3, COL5A1, FAM162A, IDUA, and PPP2R1A in ovarian cancer cells was significantly downregulated." (PMID 33281878, 2020).
breast carcinoma (1 paper, 2020). "One study found that the expression level of IDUA was significantly downregulated in breast cancer patients with visceral metastasis compared with those without visceral metastasis." (PMID 33281878, 2020).
clear cell renal cell carcinomas (1 paper, 2023). "In vitro experiments demonstrated that knockdown of IDUA inhibited the proliferation and migration of clear cell renal cell carcinoma." (PMID 38146369, 2023).
congenital heart disease (1 paper, 2020). A heart disease that is present at birth. "Taking together, our study expands the IDUA mutation spectrum and contributes to the recognition and accurate diagnosis of its impact on phenotypic expression in MPS I patients, which was previously misdiagnosed as congenital heart disease for almost a decade." (PMID 31758674, 2020).
diabetes (1 paper, 2019). "Amongst the top ranked new associations were IDUA and HAO1, representing two biological pathways of possible interest for diabetes: breakdown of glycosaminoglycans and 2-hydroxyacid oxidase activity." (PMID 31446444, 2019).
fractures (1 paper, 2019). "IDUA rs6831280 is associated with BMDs at L2-4 and TH in the elderly Chinese population with SOP and may serve as a marker for the genetic susceptibility to osteoporotic fractures." (PMID 31275456, 2019).
hemophilia B (1 paper, 2022). Hemophilia B is a form of hemophilia characterized by spontaneous or prolonged hemorrhages due to factor IX deficiency. "Similar clinical trials were performed for MPS I (NCT02702115), which is caused by mutations in the IDUA gene, and for hemophilia B (NCT02695160) patients, which is caused by mutations in the factor IX (FIX) gene." (PMID 36324900, 2022).
hepatocellular carcinoma (1 paper, 2023). A malignant tumor that arises from hepatocytes. "It has been reported that IDUA is involved in chondroitin sulfate/dermatan sulfate metabolism and glycosaminoglycan metabolism, and IDUA_GNPDA1 could be used as a beneficial prognostic factor in hepatocellular carcinoma." (PMID 36814419, 2023).
mental disorder (1 paper, 2016). A disease that has its basis in the disruption of mental process.
mucolipidosis type II (1 paper, 2025). Mucolipidosis II (MLII) is a slowly progressive lysosomal disorder characterized by growth retardation, skeletal abnormalities, facial dysmorphism, stiff skin, developmental delay and cardiomegaly. "Indeed, triclabendazole reduced the transduced GAG core proteins in the MPS model cells, including IDUA KO cells, ARSB KO cells, and GUSB KO cells, as well as in GNPTAB KO cells, a model cell for mucolipidosis type II." (PMID 40822349, 2025).
preeclampsia (1 paper, 2024). Preeclampsia is a hypertensive disorder of pregnancy that is characterized by new-onset hypertension with proteinuria presenting after 20 weeks of gestation, and depending on mild or severe forms may initially present with severe headache, visual disturbances, and hyperreflexia. "In our study, several novel predictive biomarkers were associated with late-onset preeclampsia, including IDUA, FCGR2B, and CD4." (PMID 38253981, 2024). "The biomarkers that were associated with late-onset preeclampsia were BNP, MMP-12, alpha-L-iduronidase (IDUA), PlGF, low-affinity immunoglobulin gamma Fc region receptor II-b, and T cell surface glycoprotein." (PMID 38253981, 2024).
renal cell carcinoma (1 paper, 2022). "In addition, IDUA is a novel glycolysis-related gene that is associated with the immune microenvironment in renal cell carcinoma." (PMID 35945500, 2022).
visual disorders (1 paper, 2016). "Eight positively selected genes within the tarsier lineage were implicated in several diseases associated with eye development and visual disorders (BBS2, BFSP2, IDUA, IL1A, IMPG1, RGR, SRD5A3 and TMC8)." (PMID 27708261, 2016).
tumor (6 papers, 2018 to 2024). "The protein expression of CD44, HK3, KIF20A, and IDUA was higher in the tumor tissues compared to the normal tissue, and the protein expression of GALM and TGFA was lower in tumor tissues than normal, which was consistent with our results in TCGA." (PMID 33816274, 2021). "Of the 16 metabolism-related genes, we found AOC2, IDUA, GPC2, CSPG4, TPST1, and CYP1B1 to be differentially expressed between tumor and normal tissues at the protein level." (PMID 35281080, 2022). "Of the 16 metabolism-related genes, we found that AOC2, IDUA, GPC2, CSPG4, TPST1, and CYP1B1 were differentially expressed between tumor and normal tissue at the protein level according to the Human Protein Atlas (HPA) cohort." (PMID 35281080, 2022). "Compared with normal kidney tissues, antibody stainings for ANKZF1, CD44, IDUA, KIF20A, PLOD2, and VCAN were high in ccRCC tumor tissues, whereas they were low for CHST6, HS6ST2, NDST3 and FBP1." (PMID 33836688, 2021).
metabolic disorder (4 papers, 2017 to 2024). "Mucopolysaccharidosis type I-Hurler (MPS1-H) is a rare inherited metabolic disorder caused by loss-of-function mutations in the IDUA gene leading to the complete deficiency of alpha-L-iduronidase, the enzyme involved in the degradation of glycosaminoglycans (GAGs)." (PMID 33287330, 2020).
autosomal recessive disease (2 papers, 2022 to 2025). Autosomal recessive form of disease. "IDUA encodes an enzyme that is correlated to the degradation of two glycosaminoglycans, and mutations in this gene lead to the autosomal recessive disease mucopolysaccharidosis type I." (PMID 35281080, 2022).
cancer (2 papers, 2021 to 2022). A tumor composed of atypical neoplastic, often pleomorphic cells that invade other tissues. "We succeeded in finding relatively new co-expressed genes, such as TIMELESS, IDUA, CPZ, MGC27165, C10orf56 and so on that were found to be associated with BC or other cancers until this decade." (PMID 33790307, 2021).
IDUA also shares sentences with these, for which no sentence is quoted: genetic disease (3 papers); metachromatic leukodystrophy (3); congenital metabolic disorder (2); GM1 gangliosidosis (2); Lysosomal disease (2); amyloidosis (1); ataxia telangiectasia (1); benign tumors (1); Blepharophimosis (1); Duchenne muscular dystrophy (1); Epicanthus inversus (1); familial candidiasis (1); glycogenosis (1); hemoglobinopathies (1); hemophilia (1); hereditary cancer (1); inflammatory bowel disease (1); Intellectual disability (1); junctional epidermolysis bullosa (1); juvenile open angle glaucoma (1); keratoconus (1); leukodystrophy (1); melanoma (1); Morquio-A disease (1); mucopolysaccharidosis type IVB (1); nephrotic syndrome (1); neuronal ceroid lipofuscinosis (1); osteogenesis imperfecta, type xv (1); Parkinson disease (1); Pompe disease (1).
A further 7 diseases each share a sentence with IDUA in 1 paper.